HIF1A (hypoxia inducible factor 1 subunit alpha)
Diseases named in the same sentence as HIF1A in open-access papers (continued):
Sharing a sentence is not in itself a finding about the gene and the disease.
tumor (continued). "Unfortunately, few clinical studies reported the extent of the decline in the tumor HIF-1α expression after using HIF-1α inhibitors." (PMID 36846589, 2023). "We further confirm that macrophage Syk controls HIF1α stabilization to promote tumor growth and immunosuppression." (PMID 37350973, 2023). "HIF-1α also stimulates the expression of the immune checkpoint inhibitors PD-L1, CTLA-4, and LAG-3 on tumor and tumor-associated immune and stromal cells." (PMID 37239368, 2023). "IFN-γ reduced tumor growth by increasing NO and stabilizing HIF-1α to enhance glycolytic flux in H6 cells." (PMID 37965321, 2023). "Multiple studies have indicated that continuous sorafenib treatment induces tumor hypoxia, leading to the selection of tumor clones that adapt to a hypoxic environment by activating HIF-1α and NF-κB, thereby diminishing the efficacy of sorafenib." (PMID 37576900, 2023). "Some studies have shown that HIF-1α translocates to the nucleus to regulate angiogenesis and promote tumor growth and invasion." (PMID 36334237, 2023). "The distribution of HIF-1α expression was also variable ranging from 25% to 75% distribution within the tumor specimen." (PMID 37568769, 2023). "Among the targets induced by HIF-1α, connexin 43 (Cx43) forms Gap-junctions to stabilize NK cells/tumor cells’ connection." (PMID 38071322, 2023). "With this model, we first showed that YC-1 at 5 mg/kg/day showed a strong inhibitory effect on HIF-1a expression levels in tumor xenografts." (PMID 38066600, 2023). "Under hypoxic conditions, tumor cells respond with rapid induction of transcription factor hypoxia-inducible factor 1 alpha (HIF1α) and NFκB." (PMID 36999013, 2023). "This pro-VEGF secretion effect of fructose is achieved by affecting the level of ROS and the expression of HIF1α in tumor cells." (PMID 37507736, 2023). "Hypoxia‐inducible factor 1 subunit alpha (HIF1α) expression increases in the tumor environment due to hypoxia, enhancing PD‐L1 expression in MDSCs." (PMID 37547175, 2023). "And also, HIF-1α resulted in the biological processes of glycolysis, angiogenesis, invasion, and metastasis, tumor stem cell enrichment and immunological escape." (PMID 37904441, 2023). "HIF-1α promotes tumor metastasis to distant and more oxygenated tissues through the transcriptional activation of oncogenic growth factors such as transforming growth factor-beta 3 (TGF-β3) and epidermal growth factor." (PMID 38140111, 2023). "Hypoxia-inducible factor 1α (HIF-1α) is a transcription factor that plays a major role in regulating angiogenesis during adaptation of tumor cells to nutrient-deprived microenvironments." (PMID 37906252, 2023). "Specifically, HIF-1α regulates hedgehog pathways in tumor cells, whereas hedgehog pathways regulate HIF-1α activity in hepatic stellate cells." (PMID 37255604, 2023). "Tumour‐derived lactate signalling activates macrophages via HIF1α to reach a tumour‐promoting state characterized by upregulated expression of Arg 1 and VEGF." (PMID 37060186, 2023). "This transcription factor recognizes the tandem repeats of the minimum binding sites of HIF1α and HIF2α placed in the promoter of the pHRE-Luc vector used in this study, which generated a high expression of the luciferase gene in the tumor tissue." (PMID 37765201, 2023). "Tumor cells can proliferate under hypoxic conditions and this is closely related to the activation of hypoxia-inducible factor-1α (HIF-1α) and VEGF." (PMID 37384288, 2023). "Considerable evidence shows that HIF-1α is critical for glycolysis initiation during DCs activation in tumor, which is required for DCs activation and antigen presentation, as well as effector T cells function." (PMID 37828561, 2023). "It has been reported that CAFs have been involved in regulation of tumor HIF1α to promote tumor progression." (PMID 36835352, 2023). "The macrophages exposed to hypoxia accumulate HIF1α and HIF2α, thereby promoting tumor growth through the controlled PI3K signaling pathway." (PMID 36698095, 2023).
tumor (continued). "The glycolytic switch is directed by hypoxic or normoxic activation of HIF-1α- transcription and is implemented in hostile tumor microenvironments." (PMID 37781517, 2023). "Given these key roles of HIF-1α in regulating the metabolic activity that drives tumor progression, it is critical to define the role of metabolism in directing immunity." (PMID 36614196, 2023). "Tumor hypoxia contributes to chemotherapy resistance by inducing the hypoxia-inducible factor-1α (HIF-1α) pathway." (PMID 36909187, 2023). "Blocking lactate production in tumor cells or deleting HIF-1α in MDSCs reverse anti-tumor T-cell responses and effectively inhibite tumor progression after radiotherapy for pancreatic cancer patients." (PMID 37350962, 2023). "As observed, The expression of HIF-1a was highest in xenograft tumor of nude mice treated with oe-circRNA778_006 was largest." (PMID 37938614, 2023). "Mutational inactivation of the tumour suppressor VHL gene is an early genetic anomaly in the mainstream ccRCCs, leading to enhanced expression of the HIF-1α and HIF-2α transcription factors." (PMID 37174052, 2023). "A hypoxic environment is an essential and common feature of solid tumors; in this setting, the HIF-1α activity promotes tumor cells’ adaptation to the low oxygen tension." (PMID 37175885, 2023). "The reduced entry of pyruvate into TCA and the secretion of lactate increase when oxygen concentration is low, also due to the activation of HIF1α and NRF2, not only in tumours but also in non-tumour associated cells." (PMID 36769044, 2023). "Through available data, binding PD-1 to PD-L1 on AML cell lines can increase glycolysis metabolism through AKT/mTOR/HIF-1α signaling and enhance tumor cell invasion, metastasis, and AML cell proliferation." (PMID 37735675, 2023). "In particular, HIF-1α activates the transcription of genes involved in virtually all aspects of tumor biology, inducing, for example, invasion and metastasis as well as resistance to radiation and chemotherapy, in addition to angiogenesis." (PMID 37830546, 2023). "These new data in PCa cells are consistent with the notion that TG2 is a transcriptional target of HIF-1α and enhances the survival of hypoxic tumour cell." (PMID 37160910, 2023). "TAMs play crucial roles in tumor growth, survival, and therapy resistance, which are directly correlated with HIF-1α- expression in these cells." (PMID 37520562, 2023). "Simultaneously, we also found that HIF-1a was expressed at higher levels in SKA3-overexpressing tumours of nude mice than in NC tumours, while PARP1 knockdown reversed this effect." (PMID 37821935, 2023). "In tumor cells, HIF-1α elicits an increase in pSTAT3 and autophagy pathway, promoting resistance to cytotoxic T cells (CTL)-mediated tumor cell lysis." (PMID 38071322, 2023). "The HIF-1α/VEGF axis in cytotoxic CD8+ T cells regulates tumor progression, and the deletion of VEGF-A in CD8+ T cells accelerated tumorigenesis while also altering vascularization." (PMID 37443821, 2023). "Conversely, after interference with FAAH, decreased FFA led to an insufficient substrate for the synthesis of LPA, which blocked the activation of COX-2/PGE2 signalling by HIF-1α and further inhibited the formation of tumours." (PMID 36702852, 2023). "EF24, a structurally similar substance to curcumin, inhibits HIF-1α and promotes its degradation by upregulating the von Hippel–Lindau tumor suppressor, synergistically enhancing the anti-tumor effects of sorafenib and abrogating drug resistance." (PMID 36769116, 2023). "Previous studies have found that ncRNAs can regulate tumor glycolysis by regulating HIF-1α and its downstream glycolysis-related enzymes, thereby affecting tumor radiosensitivity." (PMID 36909247, 2023). "Focusing specifically on tumors, these OnB have demonstrated efficacy in reversing hypoxic conditions, leading to a subsequent reduction in the expression of HiF-1α across various tumor types and cancer cell lines." (PMID 38063756, 2023).
tumor (continued). "Enhanced activation of the HIF-1α system in sustained hypoxia conditions within tumors leads to certain cellular changes that promote tumor progression." (PMID 36766555, 2023). "EGFR activation can increase dimer PKM2 expression and induce translocation of dimer PKM2 into the nucleus, where PKM2 acts both as a protein kinase and a transcriptional coactivator for HIF-1α in tumor tissues." (PMID 36874012, 2023). "Overall, SOX2 appears to play a complex role in hypoxia, facilitating both the expression of HIF-1α and its downstream pathways, and promoting tumor progression and invasion." (PMID 37614497, 2023). "Hypoxia-inducible factor-1α (HIF-1α) is a crucial mediator of intra-tumoral heterogeneity, tumor progression, and unresponsiveness to therapy in tumors with hypoxia." (PMID 36846589, 2023). "Both AMPK and HIF-1α are key determinates of tumour growth and progression, in the context of oxidative stress and nutrient depletion." (PMID 37233716, 2023). "TERT plays a role in the activity of telomerase and HIF1A in the cellular response to hypoxia, promoting tumour growth." (PMID 37400829, 2023). "The inhibition of HIF-1α/VEGFA can successfully suppress tumor growth, metastasis, and angiogenesis." (PMID 37239383, 2023). "The canonical family member COMMD1 is a tumour suppressor with cytoplasmic roles controlling vesicular trafficking, and nuclear roles restraining HIF-1α and NFkB activity." (PMID 37072858, 2023). "A high expression of FBP can inhibit HIF-1α, interfere with glycolysis, and hinder tumour cell proliferation, invasion, and migration." (PMID 37108242, 2023). "Further, HIF-1α enhanced the function of TGF-β1 to increase tumor cell glycolysis in hypoxia condition." (PMID 37937056, 2023). "The expression of HIF-1α and PD-L1 in the tumor was significantly downregulated by the BRD4 inhibitor." (PMID 37685868, 2023). "HIF‐1α is a key driver of glucose metabolism that promotes cell survival, migration, and angiogenesis, all of which contribute to tumor resistance to cytotoxic therapy." (PMID 37584455, 2023). "Noteworthy, we observed a reduced presence of HIF1A+ tumor cells in G3 Tert−/− mice compared to Tert+/+ mice." (PMID 37085672, 2023). "Constitutive activation of the PI3K/PDK1/AKT pathway and HIF1a pathway under low level of oxygen contribute to increased glycolysis in tumor." (PMID 37183243, 2023). "The fact that these effects were comparable to those of a synthetic HIF-1α inhibitor led to the assumption of the neoangiogenesis limitation as this is a fundamental requirement for tumor growth and spread." (PMID 37583906, 2023). "STAT3 and hypoxia-inducible factor 1-α (HIF1-α) are important transcription factors involved in M2 polarization in tumor microenvironments." (PMID 37403048, 2023). "The pVHL is a tumor suppressor and substrate-recognition component of the E3 ubiquitin ligase complex that in normoxic conditions, will ubiquitinate hydroxylated HIF-1α leading to its subsequent degradation." (PMID 37191417, 2023). "Specifically, HIF-1α-induced VEGF signaling stimulates local angiogenesis to nourish both the tumor and adjacent brain areas." (PMID 38026690, 2023). "HIF‐1α downregulates the expression of dicer by promoting ubiquitination of the E3 ligase parkin, which further inhibits known tumor suppressors, such as the microRNAs let‐7 and microRNA‐200B." (PMID 36703877, 2023). "In particular, the relationship between HIF1α, which is induced by hypoxic responses and has a key role in tumor malignancy, and HBB is not well understood." (PMID 37239002, 2023). "According to experimental data, SDH mutations can lead to succinate accumulation and subsequent stabilization of hypoxia-inducible factor-1 alpha (HIF-1α), thereby promoting tumor growth." (PMID 37492564, 2023). "VEGF is upregulated by HIF-1α during hypoxia that induces the development of blood vessels in solid tumours and promotes intravasation of cancer cells from primary tumour sites." (PMID 36656411, 2023).
tumor (continued). "In hypoxic environment, HIF1A signalling has been proven to regulate a variety of tumorigenesis and progression, such as tumor cell survival, proliferation, metastasis, and angiogenesis." (PMID 38053093, 2023). "Altogether, the immunoblot demonstrated coupling of HIF-1α and NF-κB, which is interpretable as a functional axis between two tumor-promoting transcription factors." (PMID 37583906, 2023). "O2.− stabilizes HIF-1α, promoting the hypoxic response—i.e., glycolysis, tumor cell proliferation, angiogenesis, and evasion of immune response." (PMID 36319818, 2023). "Notch was demonstrated to transcriptionally upregulate the expression of HIF-2α in certain tumor cells via a HIF1α-to-HIF2α switch." (PMID 36798826, 2023). "Mounting evidence has suggested that overexpression of HIF1α in PCa activated several signaling pathways involved in cellular differentiation, metastasis, tumor progression, angiogenesis, and resistance to castration or chemotherapy." (PMID 36841806, 2023). "Through enrichment analysis of differential genes from GEPIA2, we identified hypoxia-related genes, and through the PPI network, we determined the gene directly related to HIF1A, which plays the most critical role in the process of tumor hypoxia." (PMID 37277450, 2023). "TAMs-derived EVs maintained aerobic glycolysis of tumor cells via HIF-1α-stabilizing long noncoding RNA." (PMID 37833255, 2023). "Meanwhile, immunohistochemistry (IHC) staining showed the protein level of HIF1A was highly elevated in both iWAT and eWAT from 4T1/Ctrl mice when compared with 4T1/miR-204 KO, 4T1/Rab27a KO or tumour free mice." (PMID 37620316, 2023). "These pathways involve factors such as VEGF, hypoxia-inducible factor 1-alpha (HIF-1α), and nuclear factor-kappa B (NF-κB), which contribute to the formation of new blood vessels in the tumor microenvironment." (PMID 38089632, 2023). "HIF-1α promotes tumor cells to acquire booster proliferation, invasion and metastasis capabilities under the metabolic stress conditions in which HIF-1α degradation is inhibited." (PMID 36835352, 2023). "ccRCC tumor cell lines frequently exhibit intragenic deletions of HIF1A but express wild-type HIF2α." (PMID 37190141, 2023). "Cell RNA sequencing showed that the conditional deletion of HIF1α in tumor-infiltrating NK cells inhibited tumor growth and enriched the expression of NF-κB pathway." (PMID 36895027, 2023). "Inhibiting VEGFR2/STAT3/HIF‐1α axis signaling pathway can inhibit the proliferation, migration, and tumor angiogenesis of hucCT‐1 and RBE cells." (PMID 37329188, 2023). "By modulating collagen synthesis and collagen fiber alignment as well as integrin-ECM interactions within the TME, HIF-1α also aid tumor cell migration and metastasis." (PMID 36672326, 2023). "The inactivation of HIF-1α has been shown to enhance the effect of carboplatin on tumor cell proliferation and thus can be used as a hypoxia-centered therapy." (PMID 36672326, 2023). "Lactate increases tumor malignancy by promoting tumor small extracellular vesicle production via the GPR81/cAMP/PKA/HIF-1α axis." (PMID 38136207, 2023). "RE’s effectiveness as an anti-tumour drug has been correlated to its ability to restore vascular normalization and reduce HIF-1α expression and its related signalling pathways." (PMID 37259367, 2023). "Growth factors, prominently macrophage-colony stimulating factor (CSF-1) emanating from tumor cells, hypoxia-responsive elements like hypoxia-inducible factor 1-alpha (HIF-1α), and metabolic derivatives such as lactate play vital roles." (PMID 38035068, 2023). "They observed enhanced in vivo tumor growth of the HIPK2−/− cells while the tumor cells with HIF-1α knockout grew significantly slower compared to the control tumors." (PMID 36900356, 2023). "HIF-1α plays an essential role in promoting tumor growth by stimulating angiogenesis through various pathways, including the induction of VEGF." (PMID 37427098, 2023).
tumor (continued). "Reanalysis of CC using the TCGA database showed expression patterns between normal and tumor samples, suggesting that high expression of HIF-1α and HIF-3α led to decreased survival in patients with CC." (PMID 37692844, 2023). "The unfavorable effects of the hypoxic microenvironment in tumor tissue are mainly realized by HIF-1α, which induces pro-oncogenic gene expression to disrupt the “homeostasis” of TME." (PMID 37169756, 2023). "HBO can regulate the tumor microenvironment and improve cancer immunotherapy by targeting HIF1α, relieving tissue hypoxia, and consuming ECM." (PMID 37790761, 2023). "We found higher expression of HIF1a in tumors compared to their matched NM samples, confirming expected tumor hypoxia, and suggesting potential nutrient deprivation." (PMID 37318751, 2023). "In our previous studies, we had found that HNK and its derivative exhibited potential inhibitory effect of HIF-1α and anti-tumour properties." (PMID 37558230, 2023). "In HeLa and C33A cells with high HOTAIR expression, HIF-1α expression can be increased after radiotherapy, leading to radiation resistance and tumor growth, but this effect can be neutralized by miR-217 mimics." (PMID 37692844, 2023). "This, in turn, enhances VEGF-A production through the HIF1α and cJUN pathways, thereby promoting tumor angiogenesis within the microenvironment." (PMID 38069225, 2023). "We used a sequential, multiplex staining protocol in which six markers were analyzed simultaneously: CD15 (neutrophil marker), pan-cytokeratin (CK; tumor marker), HIF-1α, GLUT1 and HK2 (glycolytic markers), and DAPI (nuclear marker)." (PMID 36614196, 2023). "EGFR activation promotes dimer PKM2 expression and nuclear translocation to activate HIF-1α, contributing to abnormal glycolysis and tumor cell proliferation." (PMID 36874012, 2023). "The upregulation of HIF-1α and HIF-2α is observed in many cancer types, and, generally, tumor hypoxia is strongly associated with increased malignancy, poor prognosis, and resistance to various treatment strategies." (PMID 37568677, 2023). "The recruitment of microglia to the hypoxic niche is facilitated through HIF-1α downstream targets, and their motility is curtailed by hypoxia and shifted toward a pro-tumor phenotype." (PMID 37700840, 2023). "HIF-1α activates downstream genes that are critical for tumor survival and progression at the transcriptional level." (PMID 37946265, 2023). "Tumor tissue levels of CCL3 (MIP-1α) and IL-1β displayed significant positive correlation with the amount of HIF-1α in the tumor." (PMID 38273861, 2023). "For example, the compound MitoQ was shown to suppress hypoxic HIF-1α stabilization, while similarly targeted antioxidants suppressed tumor cell anchorage-independent cell growth." (PMID 36935009, 2023). "Under hypoxic environments, HIF-1α promotes the migration of CD8+ T cells into tumor tissues, and its activation leads to an increase in lactate dehydrogenase A, which converts α-KG to L-2-HG." (PMID 37563735, 2023). "Yang designed a new gold nanoparticle sensitizer that inhibits HIF-1α-mediated angiogenesis and maximizes the tumor attenuation effects of radiation therapy." (PMID 37111692, 2023). "In the absence of BNIP3, breast cancer cells are unable to eliminate dysfunctional mitochondria, which results in increased mitochondrial ROS and the upregulation of HIF-1α, a key transcription factor in tumor formation." (PMID 38067169, 2023). "Based on the observed upregulation of HIF-1α neutrophil expression in PDAC patient tumor tissue, we next sought to address the role of neutrophil-derived HIF-1α in directing PDAC disease outcomes in vivo." (PMID 36614196, 2023). "In summary, the multicellular 3D-TME effectively stimulated the CRC cells in a tumor-promoting manner, and both CA and the HIF-1α inhibitor suppressed their migratory propensity in a concentration-dependent manner." (PMID 37583906, 2023).